MIR24-2 (microRNA 24-2)
Synonyms: hsa-mir-24-2; MIRN24-2; miR-24-2; miRNA24-2
Gene: MicroRNA gene on chromosome 19 (13,836,287 to 13,836,359, reverse strand). Ensembl gene ENSG00000284387.
Pathways (Reactome):
Cellular responses to stimuli: Oncogene Induced Senescence; Oxidative Stress Induced Senescence
Gene expression (Transcription): Transcriptional Regulation by VENTX
Gene Ontology:
Biological process: miRNA-mediated post-transcriptional gene silencing
Cellular component: RISC complex
Homologues: Orthologues: dog MIR24-2 (95% identical), pig ssc-mir-24-1 (95% identical), guinea pig MIR24-2 (92% identical), rabbit ocu-mir-24-2 (77% identical), macaque MIR24-2 (74% identical), zebrafish mir24-3 (74% identical), tropical clawed frog xtr-mir-24b (71% identical). Paralogues in human: MIR24-1 (71% identical), MIR3074 (58% identical).